INS (insulin)
Diseases named in the same sentence as INS in open-access papers (continued):
Sharing a sentence is not in itself a finding about the gene and the disease.
type 2 diabetes (continued). "Studies have shown that iron regulates the role of insulin in healthy people and in people with type 2 diabetes." (PMID 32280714, 2020). "In conclusion, half of patients with newly diagnosed type 2 diabetes can respond to the short-term intensive insulin treatment and maintain a long-term drug-free glycemic remission." (PMID 32149152, 2020). "For example, intestinal microorganisms can alter the synthesis and secretion of insulin and glucagon, which is closely related to type II diabetes mellitus in animals." (PMID 32832271, 2020). "In humans, increased dietary glycine intake has beneficial effects in obesity and type 2 diabetes, including improving insulin sensitivity." (PMID 32500084, 2020). "These compounds, working as insulin sensitizers, are oral hypoglycemic agents suggested as second-line medication in the treatment of type 2 diabetes mellitus." (PMID 32937951, 2020). "FFAR1 is of particular interest because the triggering of insulin secretion is glucose-dependent, which makes it a major focus for the treatment of type 2 diabetes, as agonists will improve glycemic regulation and minimize the risk of hypoglycemia." (PMID 33139638, 2020). "Another SR–MA study revealed that ginger improved lipid profiles and benefited the glucose control, insulin sensitivity, and glycosylated hemoglobin of type 2 diabetes mellitus." (PMID 31935866, 2020). "Insulin overproduction also leads to the overexpression of other ATF2 target genes that lead to β-pancreatic cell dysfunction—pathophysiology of type II diabetes mellitus." (PMID 32993798, 2020). "Metformin has been used for many years as an agent to increase the tissue response to insulin in patients with type 2 diabetes." (PMID 32992734, 2020). "PGC-1α is a powerful regulator of energy metabolism in both health and disease; a close relationship exists among PGC-1α function, insulin sensitivity, and Type 2 diabetes." (PMID 33317634, 2020). "One promising strategy that acutely improves postprandial glycaemia for people with type 2 diabetes is through the provision of mealtime whey protein, owing to the slowing of gastric emptying and increased secretion of insulin and the incretin peptides." (PMID 33195375, 2020). "Girls also enter puberty ~2 years earlier than boys, resulting in worsening insulin sensitivity, being probably a major reason why girls develop type 2 diabetes earlier than boys." (PMID 33013688, 2020). "Two types of insulin are used in both type 1 and type 2 diabetes; a long acting or “basal” insulin, usually injected once a day, and rapid and short acting insulin, usually injected multiple times a day prior to mealtimes." (PMID 33202992, 2020). "The proportion of women with Type 2 diabetes prescribed medications different from insulin and metformin rose from 22.3% (20.5%–24.2%) to 27.3% (26.0%–28.6%)." (PMID 33692751, 2020). "Although glucagon dysregulation is as important as insulin dysregulation in type 2 diabetes, therapeutic pharmacological approaches targeting glucagon are lacking, compared with pharmacological approaches that improve insulin secretion and β-cell function." (PMID 33020399, 2020). "Treatment intensification in people with type 2 diabetes following failure of basal insulin commonly involves the addition of a rapid-acting insulin analogue (basal plus one or more prandial doses; multiple daily injections) or by a switch to premixed insulin." (PMID 32290465, 2020). "Rosella acts as an herbal medicine for type 2 diabetes and has antihyperglycemic effects through the regulation of insulin secretion." (PMID 33005201, 2020). "Type 2 diabetes is characterized by impaired insulin secretion and activity, leading to multiple metabolic abnormalities including hyperglycemia in fasted and postprandial states." (PMID 32182914, 2020). "The majority of the patients had type 2 diabetes (198 cases 90%) including 138 (62.27%) insulin-treated, 10% had type 1 diabetes." (PMID 32831070, 2020).
type 2 diabetes (continued). "Type 2 diabetes (T2D) occurs due to a progressive decline in the ability of the pancreas to secrete enough insulin as well as insulin resistance in insulin target tissues." (PMID 32277104, 2020). "The pathogenesis of type 2 diabetes reflects an unbalanced dynamic interaction between environmental factors, insulin-responsive tissues, and insulin-producing cells." (PMID 32226550, 2020). "Adenosine signaling plays a critical role in the regulation of glucose homeostasis, insulin sensitivity, and the pathogenesis of type 1 and type 2 diabetes." (PMID 32527043, 2020). "Interstitial glucose levels were monitored for 14 days in 26 insulin-treated patients with type 2 diabetes using the FGM system." (PMID 32377186, 2020). "Nonetheless, its inhibitory effects at PTP1B, altering the insulin signaling pathway, represents a new therapeutic target to treat diabetes type 2." (PMID 32636724, 2020). "In patients with type-II diabetes, inhaled insulin can be used as a monotherapy or in combination with oral agents or subcutaneous longer-acting insulin." (PMID 32785196, 2020). "Evidence for the involvement of insulin in brain aging is provided by the correlation between type 2 diabetes and neurodegenerative dementias and it culminates in the annotation of Alzheimer’s disease as “diabetes type 3”." (PMID 32138778, 2020). "Recent results in insulin-naive individuals with type 2 diabetes revealed similar HbA1c reductions for insulin degludec and glargine U300." (PMID 31984443, 2020). "The goal of the present study was to evaluate retinal insulin signal transduction in a common mouse model of type 2 diabetes, the db/db mouse." (PMID 32432228, 2020). "Western medicine's treatment of type 2 diabetes with oral medicine revolves around aspects such as promoting insulin secretion, improving insulin resistance, and delaying the absorption of glucose in the gastrointestinal tract." (PMID 32756078, 2020). "More precisely, sleep-associated breathing disorder (p = 0.011), hypertriglyceridemia (p = 0.007), fatty liver disease (p = 0.031) and type 2 diabetes that requires insulin treatment (p = 0.014) were more frequent in men." (PMID 33192409, 2020). "People with type 2 diabetes received a variety of glucose-lowering treatments: 20.1% were treated with diet only, 61.7% received oral glucose-lowering medication, 5.2% received insulin and 13.0% were treated with a combination of oral medication and insulin." (PMID 32185461, 2020). "Type 2 diabetes mellitus (T2DM) is distinguished as a metabolic dysfunction described by high-blood glucose in relation to comparative insulin deficiency and resistance of insulin." (PMID 32908933, 2020). "It reduces muscle mass loss during weight loss in frail older adults with obesity and also improves insulin sensitivity of the muscles in older adults with obesity and type 2 diabetes." (PMID 33379181, 2020). "Although for people with early stage type 2 diabetes (T2D), a healthy diet, exercise, and weight loss may be sufficient to maintain near normal BG, people with type 1 diabetes (T1D) or progressed T2D require insulin therapy and more intensive glucose monitoring." (PMID 32975198, 2020). "Studies have shown that PQR can improve cellular immune response and mitochondrial function, increase insulin production, reduce pancreatic cell death, and improve postprandial blood glucose in patients with type II diabetes mellitus." (PMID 33381041, 2020). "The results of this cohort study show no consistent statistically significant differences in rates of MI, CVA, CHF hospitalizations, CVD mortality, or overall mortality between adults with type 2 diabetes initiating human vs analogue insulin treatment." (PMID 31977057, 2020). "It has been reported that histidine treatment regulates hepatic glucose metabolism in type 2 diabetes, and improves insulin sensitivity." (PMID 31963766, 2020).
type 2 diabetes (continued). "We used a type 2 diabetic mouse model (db/db) and mouse podocytes exposed to palmitic acid for 24 h followed by an insulin stimulation." (PMID 33303821, 2020). "Type 1 diabetes (also referred to Juvenile-onset) is caused due to ineffective production of insulin produced by beta cells of the pancreas whereas Type 2 diabetes (also known as adult-onset) arises due to the ineffective use of insulin inside the body." (PMID 32392841, 2020). "While elevated glucose levels are a sign of reduced insulin secretion or action and also a proxy of type 2 diabetes and cardiovascular disease lower levels of fasting glucose are associated with all-cause mortality." (PMID 32848869, 2020). "In this study, we demonstrated that P4-mediated PGRMC1 induction increases gluconeogenesis under insulin-resistant conditions such as type II diabetes." (PMID 33005004, 2020). "Enrichment analysis strongly reinforced the robustness of our study, highlighting many processes related to pancreatic cancer (PDA genesis, type II diabetes mellitus onset, and insulin secretion)." (PMID 32245227, 2020). "The essential trace mineral Cr has been suggested to have beneficial effects in individuals with type 2 diabetes as evidenced by enhance insulin sensitivity and glucose transport at the molecular level." (PMID 32961883, 2020). "Currently, it has been shown that elderly type 2 diabetes patients have relatively low serum magnesium levels, which correlates with reduced insulin sensitivity." (PMID 32952944, 2020). "There is growing evidence from animal models that leptin and adiponectin play a critical role in type 2 diabetes prevention and control by promoting beta-cell function and survival, improving insulin sensitivity, and regulating glucose metabolism." (PMID 32131811, 2020). "Type 2 diabetes mellitus (T2DM) is a common, chronic metabolic disease caused by insufficient insulin secretion and/or activity, leading to chronic hyperglycaemia." (PMID 32851096, 2020). "Insulin-stimulated glycogen synthesis is decreased in individuals with type 2 diabetes and metabolic syndrome, accounting for most of the differential in whole-body glucose disposal." (PMID 32591558, 2020). "EP3 inhibition also enhances insulin secretion in human islets isolated from donors with type 2 diabetes." (PMID 32350565, 2020). "It has been demonstrated that E2F1 essentially involved in hyperlipidemia and hyperglycaemia during resistance to insulin and abnormally increased in type 2 diabetes." (PMID 32884568, 2020). "Sleep duration is independently associated with several CVH metrics, such as weight status and hypertension, and with insulin sensitivity, which can lead to type 2 diabetes." (PMID 32530395, 2020). "And also in some studies, increasing ferritin levels have been displayed to be associated with lipemia, elevated blood glucose, and fasting insulin, forecasting incident type 2 diabetes in prospective studies." (PMID 32280714, 2020). "With support within the UK from NHS England for the use of LED in those recently diagnosed with type 2 diabetes, this study provides further evidence for promoting their use for type 2 diabetes, including those treated with insulin." (PMID 32049634, 2020). "IR, as the basis of the onset of type 2 diabetes, is defined as the reduced ability of insulin-sensitive tissues to respond to insulin, and plays a key role in the development of metabolic diseases." (PMID 32248799, 2020). "In recorded clinical data, administering chromium compounds improved insulin sensitivity in patients with type 2 diabetes." (PMID 32260278, 2020). "A study on individuals with type 2 diabetes who consumed 50 g of whey or placebo with a high glycemic breakfast found that glucose levels were reduced 28% and insulin increased 105% after the protein preload." (PMID 33322540, 2020).
type 2 diabetes (continued). "Most articles published so far showed that omentin concentrations were down-regulated in insulin-resistant states such as obesity, polycystic ovary syndrome, gestational diabetes mellitus, and type 2 diabetes." (PMID 32326011, 2020). "All the mounting inconsistencies and paradoxes in the insulin resistance concept along with the limited success of type 2 diabetes treatment warrant a re-examination of the foundational concepts." (PMID 33365205, 2020). "It promotes insulin-sensitizing, fat-burning, and anti-atherosclerotic actions, thereby effectively counteracting several metabolic disorders, including type 2 diabetes, obesity, and cardiovascular diseases." (PMID 32283840, 2020). "Glargine U300 is a concentrated formulation of glargine U100 and has also been shown to be as effective as glargine U100 in terms of glycaemic control in individuals with type 2 diabetes, but with a higher (12–14%) basal insulin dose requirement." (PMID 31984443, 2020). "Among the 74 HHS patients, all patients were received continuous intravenous low-dose insulin infusion in the early stage of treatment according to China guideline for type 2 diabetes." (PMID 33317485, 2020). "In 285 patients with type 2 diabetes, a therapy with bedtime basal insulin added to metformin was started due to failure to achieve a glycaemic goal." (PMID 32316649, 2020). "The secretion of glucagon was higher during oral glucose administration in participants with type 2 diabetes, suggesting insufficient glucagon secretion suppression by insulin and GLP-1 in these individuals." (PMID 32385603, 2020). "For example, since lipid accumulation is promoted by insulin resistance, some pharmacological medications used in type II diabetes, such as biguanides and thiazolidinediones (TZDs), have been employed." (PMID 33348908, 2020). "Secondary outcome measures are fasting hormones/endocrine factors (insulin, glucose, C-peptide, Pro-insulin, adiponectin, 17-beta-estradiol, free fatty acids) related to the pathogenesis of type 2 diabetes." (PMID 32154432, 2020). "Another trial involving patients with type 2 diabetes and nephropathy reported that changes in HbA1c, fasting plasma insulin and HOMA‐IR in response to a CCR2 inhibitor, CCX140‐B, were not significant compared with the response to the placebo." (PMID 32704573, 2020). "Type 2 diabetes (T2DM) is a metabolic disease that is directly caused by an impairment of insulin secretion and/or abnormalities in insulin action." (PMID 32917052, 2020). "Increased intake of high quality dietary protein has been reported to improve insulin sensitivity in older adults with type 2 diabetes who have a normal weight or are overweight." (PMID 33379181, 2020). "Persons affected with type 1 diabetes are unable to generate insulin while individuals detected with type 2 diabetes fail to respond to insulin and in the long run cannot produce insulin." (PMID 32698547, 2020). "Findings showed that dysfunction or decreased expression of ciliary genes impairs beta-cell proliferation and insulin secretion in the pancreas and promotes the development of type 2 diabetes in rodents and humans." (PMID 33139642, 2020). "A new special reimbursement scheme (SRS) for non-insulin medications used for treatment of hyperglycaemia in type 2 diabetes (T2D) was implemented in Finland on January 1, 2017." (PMID 33246453, 2020). "In obese individuals with insulin-treated type 2 diabetes, pramlintide dose-dependently reduces body weight." (PMID 33488526, 2020). "This occurrence can either develop on a background of type 1 diabetes due to an abnormal increase in weight from physiological growth spurt in adolescents or from high insulin dosage developing on a background of type 2 diabetes." (PMID 33209162, 2020).
type 2 diabetes (continued). "While the etiologies of the two primary forms of diabetes are clearly different, Type 1 Diabetes (T1D) and Type 2 Diabetes (T2D) both result in decreased functional β-cell mass (defined as changes in β-cell survival, proliferation, and insulin secretion)." (PMID 33256225, 2020). "Here, as a consequence, the insulin release from senescent β islet cells decreases, thereby contributing to the pathogenesis of type 2 diabetes." (PMID 32369550, 2020). "Two different PPARγ agonists, rosiglitazone and pioglitazone, are insulin-mimetic drugs used in type 2 diabetes with high overall potential in reducing influenza virus infection." (PMID 33312199, 2020). "GLP‐1 is another hormone that regulates glucose metabolism by promoting the release of insulin during post‐prandial phases of ingestion, and is a therapeutic target of type 2 diabetes medications." (PMID 32512650, 2020). "After being fed a high-fat diet, wild-type mice developed type 2 diabetes; however, lymphotoxin-knockout-mice remained euglycemic and insulin-sensitive." (PMID 31480185, 2020). "Premix insulin formulations are a well-established treatment for type 2 diabetes and can be administered shortly before meals as often as once, twice, or thrice daily." (PMID 32396624, 2020). "The type II diabetes pathway was also identified as enriched in the EPI; this includes genes encoding insulin and IGF receptors as well as downstream PI3K signalling effectors, and further suggested that modulating IGF signalling would be of interest." (PMID 32034154, 2020). "Saturated fatty acids such as palmitate contribute to the development of Type 2 Diabetes by reducing insulin sensitivity, increasing inflammation and potentially contributing to anabolic resistance." (PMID 33101053, 2020). "Though patients with type 2 diabetes are characterized by insulin conflict, which revenue their reaction to insulin blunted, accordingly affecting hyperglycemia." (PMID 32880218, 2020). "It has become increasingly apparent that chronic elevation of plasma free fatty acids (FFAs) played an essential role in the impairment of insulin-stimulated glucose uptake in obesity and type 2 diabetes." (PMID 33062046, 2020). "Are there significant differences in cardiovascular outcomes in adults with type 2 diabetes who use human insulin compared with those who use analogue insulin?" (PMID 31977057, 2020). "Type 2 diabetes and its precursor, prediabetes, are characterized by impaired insulin sensitivity and increasing circulating blood glucose concentrations." (PMID 32431698, 2020). "Type II diabetes refers to the inability of the organism to properly regulate and sense insulin, known as resistance to insulin." (PMID 33182581, 2020). "This review aims to summarize and provide an update on the epidemiological and mechanistic evidence linking obesity and type 2 diabetes with cancer, focusing on the roles of insulin, lipids, and adipose tissue." (PMID 33604295, 2020). "Physical inactivity, low mitochondrial function, increased intramyocellular lipid (IMCL) deposition and reduced insulin sensitivity are common denominators of chronic metabolic disorders, like obesity and type 2 diabetes." (PMID 32185462, 2020). "Non-insulin-dependent Type 2 Diabetes Mellitus (T2DM) is a controllable chronic disease characterized by a chronic hyperglycemia that occurs when the body cannot use or produce insulin properly." (PMID 32102379, 2020). "Older patients with type 2 diabetes receive insulin more frequently, and it is likely this trend is extended to patients with dementia." (PMID 32741836, 2020). "Since obesity is associated with the development of type II diabetes, we performed glucose tolerance tests (GTT) and insulin tolerance tests (ITT) on the mice on HFD or control diet." (PMID 32730300, 2020). "By disease severity, visit adherence measures were highest for people with type 2 diabetes on insulin with 17.4% achieving all measures." (PMID 33054756, 2020).